DTX3 (deltex E3 ubiquitin ligase 3)
Description:
Functions as an ubiquitin ligase protein, and regulates Notch signaling. By promoting the ubiquitination and subsequent degradation of target proteins, it can block activation of the Notch signaling pathway, potentially acting as a tumor suppressor in human cancers. [Isoform 3]: Involved in the angiogenic EPHB4 kinase degradation in cancer cell.
Synonyms: Deltex3; RNF154; FLJ34766
Tractability: PROTAC: its protein half-life has been measured.
Gene: Protein-coding gene on chromosome 12 (57,604,484 to 57,609,804, forward strand). Ensembl gene ENSG00000178498.
Subcellular location: Cytoplasm; Nucleus
Subcellular location (Human Protein Atlas): Nucleoli; Nucleoplasm; Golgi apparatus
Gene Ontology:
Molecular function: protein binding; ubiquitin protein ligase activity
Biological process: regulation of Notch signaling pathway; Notch signaling pathway; protein ubiquitination
Cellular component: cytoplasm; nucleus; nucleoplasm
Genetic constraint (gnomAD): Loss-of-function variants: 10 observed, 28.49 expected, observed/expected ratio (o/e) 0.35, 90% interval 0.22 to 0.6. The upper end of that interval is the gene's LOEUF score, 0.6, which puts it in group 2 of 6, group 1 being the genes least tolerant of losing a copy. Missense variants: 318 observed, 477.78 expected, observed/expected ratio (o/e) 0.67, 90% interval 0.61 to 0.73. Synonymous variants: 169 observed, 196.01 expected, observed/expected ratio (o/e) 0.86, 90% interval 0.76 to 0.98.
Homologues: Orthologues: chimpanzee DTX3 (100% identical), pig DTX3 (99% identical), macaque DTX3 (99% identical), dog DTX3 (98% identical), rabbit DTX3 (93% identical), mouse Dtx3 (92% identical), rat Dtx3 (92% identical), tropical clawed frog dtx3 (74% identical), zebrafish dtx3 (48% identical), tropical clawed frog dtx3-like (40% identical). Paralogues in human: DTX3L (35% identical), DTX2 (30% identical), DTX4 (27% identical), DTX1 (25% identical).
Diseases named in the same sentence as DTX3 in open-access papers:
DTX3 is named in the same sentence as 21 diseases in open-access papers, as found by Europe PMC text mining. Sharing a sentence is not in itself a finding about the gene and the disease. The quoted sentences say what the papers report.
breast carcinoma (7 papers, 2021 to 2025). "One of these exceptions is offered by a study correlating increased copy number of DTX3 in a cohort of breast cancer patients where DTX3 was associated with a cancer-driving effect along with poor outcome." (PMID 37443713, 2023). "DTX3 acts as a driver of proliferation in luminal breast cancer and its amplification was linked to a poor outcome in patients." (PMID 36476410, 2022). "The cumulative risk of death from breast cancer for cases with mean DTX3 copy number < 5 was 29% (95% CI 26–33) ten years after diagnosis." (PMID 33616774, 2021). "Ten years after diagnosis, the cumulative risk of death from breast cancer for cases with mean DTX3 copy number < 4 was 29% (95% CI 26–33)." (PMID 33616774, 2021). "Furthermore, DTX3 amplification was associated with poor prognosis in this subgroup of breast cancer patients." (PMID 33616774, 2021). "DTX3 was reported as one of the eight essential genes for cell proliferation in luminal-subtype breast cancer according to an integrated genomic approach." (PMID 38467827, 2024). "Gene amplification of DTX3 was also proved to have impacts on overall survival of luminal subtype breast cancer." (PMID 33403043, 2021). "There was a significant relationship between DNA copy number alteration and mRNA expression of DTX3 in luminal subtype breast cancer." (PMID 33403043, 2021). "Further studies are needed to elucidate the role of DTX3 copy number increase on prognosis in breast cancer." (PMID 33616774, 2021). "In conclusion, we found that DTX3 copy number increase was present in a small proportion of breast cancer cases." (PMID 33616774, 2021). "In this study, we describe DTX3 copy number in breast cancer primary tumours and corresponding axillary lymph node metastases, and studied associations with molecular subtype, proliferation and prognosis." (PMID 33616774, 2021). "In the Cox regression analyses, the rate of death from breast cancer was higher among cases with mean DTX3 copy number ≥ 5, compared to mean < 5 (HR 3.1 (95% CI 1.5–6.7))." (PMID 33616774, 2021). "We identified DTX3 copy number increase in a low proportion of breast cancer cases (4.2% of cases had mean DTX3 ≥ 4, and 1.7% of cases had mean DTX3 ≥ 5)." (PMID 33616774, 2021). "DTX3 has been identified as a driver of proliferation in luminal breast cancer." (PMID 33616774, 2021). "Therefore, if DTX3 exerts its influence on prognosis through proliferation, a study of the prognostic effect of DTX3 copy number increase among younger breast cancer patients would be of interest." (PMID 33616774, 2021). "In this study, we used fluorescence in situ hybridization (FISH) on a historic, well-characterized cohort of Norwegian breast cancer patients to characterize DTX3 copy number in 542 formalin-fixed, paraffin-embedded primary breast cancers and their corresponding lymph node metastases." (PMID 33616774, 2021). "Precision may be influenced both by the number of cases, the number of breast cancer deaths in the study population, and the distribution of cases between the categories of DTX3 copy number status." (PMID 33616774, 2021). "DTX3 copy number increase was present in a small proportion of breast cancer cases." (PMID 33616774, 2021). "In our study, regardless of cut-offs for DTX3 copy number, point estimates showed that patients with DTX3 copy number increase had higher risks of death from breast cancer compared to cases without copy number increase." (PMID 33616774, 2021). "A previous study has shown that DTX3 is a driver of proliferation in luminal (non-basal) breast cancer." (PMID 33616774, 2021). "Using fluorescence in situ hybridization, we assessed DTX3 and chromosome 12 centromere (CEP12) copy number in 542 primary breast cancers and 117 lymph node metastases, from a well-described cohort of Norwegian breast cancer patients." (PMID 33616774, 2021).
esophageal cancer (5 papers, 2021 to 2023). A primary or metastatic malignant neoplasm involving the esophagus. "Meanwhile, the expression of DTX3 in esophageal cancer tissue and cell lines is abnormally downregulated." (PMID 34513839, 2021). "In a recent study of oesophageal cancer, DTX3 was found to increase degradation of NOTCH2 and reduce proliferation and migration of oesophageal cancer cells." (PMID 33616774, 2021). "However, DTX3 plays a contradictory role in the progression of esophageal cancer, during which it suppresses tumorigenesis by promoting the ubiquitination and degradation of NOTCH2, a key protein implicated in cell proliferation and cell-fate determination." (PMID 35098394, 2022). "Another possibility to explain the results of this DTX3-NOTCH axis in esophageal cancer cells, supported by other studies on DTX3 heterodimeric and heterogenous complexes formation is that DTX3 may require an additional component in order to bind and regulate NOTCH in vivo." (PMID 37443713, 2023). "It was reported that the expression of DTX3, acted as an anti-oncogene, was negatively correlated with NOTCH2 and suppressed proliferation and tumorigenicity of human esophageal carcinoma cells." (PMID 33403043, 2021). "DTX3 inhibits the proliferation and tumorigenicity of esophageal cancer cells and promotes the ubiquitination and degradation of Notch2." (PMID 34513839, 2021). "On the opposite side, a study in esophageal carcinoma cells (KYSE150, TE-1, Eca-109) with exogenous expression of DTX3 exerted tumor suppressing functions and found DTX3 to interact, ubiquitinate and partially colocalize with NOTCH2." (PMID 37443713, 2023).
ovarian carcinoma (3 papers, 2022 to 2024). A malignant neoplasm originating from the surface ovarian epithelium.
colon adenocarcinoma (2 papers, 2021 to 2022). "A significant downregulation of DTX3 was observed in colon adenocarcinoma (n = 275) and rectum adenocarcinoma (n = 92) tissues in comparison with normal tissues (n = 349 and n = 318 respectively)." (PMID 35098394, 2022).
colorectal tumors (2 papers, 2010 to 2022). "The expression of DTX3 in colorectal tumors and normal colorectal tissues was first assessed using the GEPIA database." (PMID 35098394, 2022).
hepatocellular carcinoma (2 papers, 2021). A malignant tumor that arises from hepatocytes. "It was discussed that the transcriptional change of DTX3 was a direct consequence of the activation of E2F transcription factors and regulated the expansion of hepatocellular carcinoma cells." (PMID 33403043, 2021).
colorectal cancer (1 paper, 2024). A primary or metastatic malignant neoplasm that affects the colon or rectum. "DTX3 governs the growth of colorectal cancer cells by regulating E2F1 and the downstream genes CDC2 and cyclin D332." (PMID 38992083, 2024).
gastric cancer (1 paper, 2024). A primary or metastatic malignant neoplasm involving the stomach.
lymph node metastasis (1 paper, 2021). "DTX3 expressions were relevant to the cervical lymph node metastasis of patients with PTC." (PMID 33403043, 2021).
poisoning (1 paper, 2024). A condition or physical state produced by the ingestion, injection, inhalation of or exposure to a deleterious agent. "The okadaic acid (OA)-group toxins, including OA, dinophysistoxin-1 (DTX1), dinophysistoxin-2 (DTX2), and dinophysistoxin-3 (DTX3), cause diarrheic shellfish poisoning in humans." (PMID 38147248, 2024).
triple-negative breast carcinoma (1 paper, 2021). An invasive breast carcinoma which is negative for expression of estrogen receptor (ER), progesterone receptor (PR), and human epidermal growth factor receptor 2 (HER2). "Furthermore, DTX3 acts as a tumor suppressor gene in triple-negative breast cancer and is expressed at a low level, which hinders its ubiquitination and degradation ability toward Notch4 and its ability to effectively inhibit triple-negative breast cancer metastasis." (PMID 34513839, 2021).
tuberculosis (1 paper, 2024). A chronic, recurrent infection caused by the bacterium Mycobacterium tuberculosis. "However, links between FAM84B, HSZFP36, and DTX3 and tuberculosis remain uncharacterized." (PMID 38890657, 2024).
tumor (7 papers, 2010 to 2024). "We aimed to assess a possible association between DTX3 copy number status in the primary tumours, and molecular subtype, proliferation and prognosis." (PMID 33616774, 2021). "Interestingly, at the time of the present review, with a few exceptions, DTX3 has been found associated with tumor suppressing effects in human cancer." (PMID 37443713, 2023). "Furthermore, we studied whether there was an association between DTX3 copy number status in the primary tumours and in the corresponding lymph node metastases." (PMID 33616774, 2021). "DTX3 displayed tumor-suppressing effects also in colorectal cancer cells via regulation of E2F1 and its cell cycle-target genes." (PMID 37443713, 2023). "Deltex E3 ubiquitin ligase 3 (DTX3), a member of the deltex family, plays an essential role in tumor development and the survival outcome of cancer patients." (PMID 35098394, 2022). "In conclusion, DTX3 plays an indispensable role in promoting tumor cell growth and mediating cell cycle-related proteins in CRC." (PMID 35098394, 2022). "In ductal breast cancer, the amplification of DTX3 is correlated with high proliferation of tumor cells and a poor prognosis." (PMID 34513839, 2021). "Deltex E3 ubiquitin ligase 3 (DTX3) plays an essential role in tumor development and may predict the outcome of cancer patients." (PMID 35098394, 2022). "However, a recent study reported the anti-tumor effect of DTX3 in esophageal carcinoma by suppressing the proliferation and migration of tumor cells." (PMID 35098394, 2022). "The roles of DTX3 in tumor development have been extensively investigated." (PMID 34513839, 2021). "We found few cases with DTX3 copy number increase in the primary tumours." (PMID 33616774, 2021). "Furthermore, point estimates showed that a higher proportion of cases with DTX3 copy number increase had histological grade III tumours, compared to cases with low copy number." (PMID 33616774, 2021). "Compared to cases without DTX3 copy number increase, point estimates showed that tumour proliferation and histological grade was higher, and prognosis was poorer for patients with DTX3 copy number increase." (PMID 33616774, 2021). "The gene Dtx3, which showed differential regulation by RNA-sequencing, was not differentially expressed in the larger set of tumor samples." (PMID 25906746, 2015).
cancer (6 papers, 2021 to 2023). A tumor composed of atypical neoplastic, often pleomorphic cells that invade other tissues. "DTX3 is an understudied E3 ubiquitin ligase that has been reported to regulate the ubiquitination and stabilization of endogenous proteins in cancer cells." (PMID 35098394, 2022). "We observed that when DTX3 copy number increase was present, it was seen in the majority of cancer cells in all three TMAs." (PMID 33616774, 2021). "To explore the significances of DTX3 in PTC, we searched GEPIA websites to compare the expressions of DTX3 in different carcinomas and normal tissues of TCGA database." (PMID 33403043, 2021). "DTX3 is an E3 ligase that targets NOTCH2 and activates proliferation in cancer." (PMID 36790929, 2023).
DTX3 also shares sentences with these, for which no sentence is quoted: aortic stenosis (1 paper); bladder urothelial carcinoma (1); breast tumors (1); ovarian serous cystadenocarcinoma (1); Papillary Thyroid Carcinoma (1); prostate adenocarcinoma (1); rectum adenocarcinoma (1).